SOX10 (SRY-box transcription factor 10)
Diseases named in the same sentence as SOX10 in open-access papers (continued):
Sharing a sentence is not in itself a finding about the gene and the disease.
tumor (continued). "SOX10 exhibited a clear nuclear staining pattern with minimal leak into the cytoplasmic region of a cell and served as a useful marker in identifying tumour cells." (PMID 35664673, 2022). "These ROIs (1–3 per tumor) which exhibited viable tumor cells and reliable SOX10 expression were selected by the pathologists." (PMID 35058553, 2022). "Given the uneven distribution of SOX10+ cells in the tumor sections, visual estimates of percentage tumor nuclei in the region-of-interests (ROIs) were determined by pathologists who were blinded to treatment." (PMID 35058553, 2022). "Recent publications reported SOX10 as a promising target, allowing the transformation of an immunological “cold” tumor into a “hot” one." (PMID 36551603, 2022). "By immunohistochemistry, the tumor shows variable immunoreactivity for S100-protein, SOX10, and MITF, as well as specific melanocytic markers such as MelanA and HMB-45." (PMID 34943200, 2021). "Among the genes upregulated in the atypical tumor compared to the nevus were: SOX10, the receptor tyrosine kinases ROS1 and NTRK3, PLA2G2A, and HOXA11, while DUSP2, PDGFD, and ELN were downregulated." (PMID 35052351, 2021). "The majority of tumour cells began to express high levels of SOX10 in white matter, including in myelinated fibres inside the tumour bulk." (PMID 33846316, 2021). "Our scRNA-seq data showed that both oligodendrocytes and tumor stem cells express Olig2, and that oligodendrocytes can be distinguished from stem cells by the expression of Sox10." (PMID 34021242, 2021). "To functionally assess effects of this programme on tumour cell phenotypes, we overexpressed SOX10 in a panel of patient-derived GSC lines." (PMID 33846316, 2021). "While in our study only 2/20 STS had immunoreactivity for SOX-10 and an additional tumor expressed SOX10 RNA levels above the cutoff, five cases in the OSCT group had a strong immunoreactivity for SOX-10 and SOX10 RNA levels above the cutoff." (PMID 34422947, 2021). "We do note, however, that the tumours in our study as well as human TNBCs express transcriptional regulators of alveologenesis such as Elf5, Sox10, Foxc1 and Cebpb." (PMID 33686070, 2021). "Here, we have shown that the observed induction of Sox10 in SLK-/- NDL tumor cells is dependent on a novel enhancer located at about −7kb upstream of the putative Sox10 start site." (PMID 33985544, 2021). "EdU labelling revealed a marked decrease in the total number of proliferating tumour cells in SOX10 OE compared to Control lesions." (PMID 33846316, 2021). "We next xenotransplanted five SOX10+ GSC lines (three of which were freshly dissociated from primary tumours) and examined their behaviour in white matter." (PMID 33846316, 2021). "Although SOX10-mediated differentiation was most pronounced in invasive tumour cells that infiltrate the corpus callosum, normal oligodendrocyte maturation is accompanied by a progressive loss of migratory potential." (PMID 33846316, 2021). "To understand the mechanisms responsible, we examined Control and SOX10 OE tumours at 4 weeks post implantation by immunofluorescence analysis." (PMID 33846316, 2021). "An analysis of xenografted tumor tissues from the mice revealed that tumors derived from SOX10 knockdown cells (shSOX10 + EV) had lower expression of GAPDHS than those derived from the control group (NTC + EV)." (PMID 34249897, 2021). "Immunohistochemistry revealed that the tumor was S-100(+), SOX10(−), CD34(+), SMA(partially+), DOG-1(+), CD117(+), KI-67 (positive for 20% + of the subjects and 40% + of the hotspots), and SDHB(−)." (PMID 33879132, 2021). "MelanA, HMB-45, MITF, S100-protein, and SOX10 immunoreaction confirmed the melanocytic differentiation of this tumor." (PMID 34943200, 2021). "Surprisingly, SOX10 OE tumours appeared less diffuse and migrated much shorter distances than controls." (PMID 33846316, 2021).
tumor (continued). "The diagnosis was confirmed immunohistochemically by strong positive reaction of the tumor cells to S100, SOX10, HMB-45, and Melan A. To confirm the presence of Bartonella organisms, PCR analysis was performed in 6 cases and was positive." (PMID 34165046, 2021). "Consistent with our previous in vitro results, the SOX10 knockdown group (shSOX10 + EV) in the OCM1 cell line exhibited significantly slower tumor growth than the control group (NTC + EV)." (PMID 34249897, 2021). "A similar differentiation pattern was also found in patient tissue, where only few SOX2+ tumour cells upregulated SOX10 in intact myelin." (PMID 33846316, 2021). "Our data show that AKT can directly phosphorylate Sox9 in vitro at serine 181 and that AKT inhibition blocks Sox9 phosphorylation and Sox10 expression in SLK(-/-) tumor cells." (PMID 33985544, 2021). "In line with the transcriptomic data, JUN was also expressed by SOX10- cells such as ganglionic-like tumor cells in GNs and tumor cells in NBs." (PMID 33712610, 2021). "To test this more directly, we performed intracranial transplantations of luciferase and GFP-tagged G144 cells transduced with SOX10 OE or Control lentiviruses and monitored tumour growth and disease-free survival." (PMID 33846316, 2021). "SOX10 knock-out tumours had a significantly faster growth rate than controls, as measured by longitudinal bioluminescence imaging and analysis of EdU incorporation." (PMID 33846316, 2021). "The proportion of SOX10+/HuNu+ tumour cells was highest in heavily infiltrated, fluoromyelin negative, white matter areas, as compared to dye-positive, low tumour-density, myelin regions in four independent xenografts." (PMID 33846316, 2021). "Strikingly, early lesions and tumor-derived cell lines express high levels of Sox10, a marker of TNBC." (PMID 33985544, 2021). "SOX10+ tumour cells were significantly less proliferative than tumour cells that remained SOX10- within the same region and occasionally expressed the immature oligodendrocyte markers CNP and CC1, but were again negative for the mature marker MBP." (PMID 33846316, 2021). "Like the parent tumor, 2XSB cells were immunoreactive for Sox10 (80–100% positivity), nestin (90–100% positivity) and S100β (80–100% positivity)." (PMID 33707600, 2021). "Nuclear SOX10 (n = 60/61) or cytoplasmic MLANA (n = 60/61) expression was detected in nearly all tumour cores, as expected." (PMID 33918976, 2021). "Mechanistically, tumour cell differentiation is driven by selective white matter upregulation of SOX10, a master regulator of normal oligodendrogenesis." (PMID 33846316, 2021). "Differentiated SOX10+/EdU− tumour cells were only found in the CC, confirming that the white matter selectivey promotes partial GBM differentiation." (PMID 33846316, 2021). "Strikingly, we found a significant increase in the number of SOX10+ cells in Pranlukast-treated tumours, which was accompanied by a dramatic reduction in proliferation relative to saline-treated controls." (PMID 33846316, 2021). "In the CNS, SOX10 is an oligodendrocytic marker gene, and its activity is an example of tumour cells co-opting a developmental pathway to escape the terminal cell differentiation state." (PMID 33339831, 2020). "We find that H3.3K27M epigenetically activates a transcriptome, enriched for PRC2 and SOX10 targets, that overrides developmental and tissue specificity and is conserved between H3.3K27M-mutant mouse and human tumours." (PMID 33277484, 2020). "Densitometric analysis of the agarose gel electrophoresis of the PCR products from normal uvea samples showed considerably lower positivity compared to tumor samples (nestin: p = 0.007; SOX10: p = 0.004)." (PMID 33255843, 2020). "These analyses identify the oligodendrocyte precursor marker and chromatin modifier SOX10 as a master regulator in RTK I-subtype tumours." (PMID 33339831, 2020).
tumor (continued). "Immunohistochemically, tumor cells are focally positive for S100 protein (<50% of cases), SOX10 (<70% of cases), and GFAP (20–30% of cases)." (PMID 32867125, 2020). "Fbxw7α promotes ubiquitination mediated SOX10 turnover through the cyclobutane pyrimidine dimer domain of SOX10, thereby inhibiting tumor progression." (PMID 33344444, 2020). "H&E staining of whole-brain sections showed that control tumours exhibit a fairly defined area of the tumour bulk and a marginal zone of tumour cells invading the surrounding tissue while in the case of SOX10 KD cells tumour boundaries appear more disrupted." (PMID 33339831, 2020). "To ensure that the tumors were the result of outgrowth of 4C-HA-MITF transformed cells, we investigated and confirmed the levels of HA-MITF and SOX10 in the tumor xenografts by Western blotting and RT-PCR, and TYR by RT-PCR." (PMID 32605315, 2020). "We found that SOX10 expression is higher in RTK I than in MES tumours, and observed the same trend in proneural and MES5 gene expression." (PMID 33339831, 2020). "SOX10 is over-expressed in RTK I tumours, correlating with genic hypomethylation and increased H3K27ac signal." (PMID 33339831, 2020). "Whereas higher expression of SOX10, OCLN, ACSL4, XIAP, and ERCC5 was associated with a lower risk of death from the tumor (HR < 1)." (PMID 33153038, 2020). "Anti-apoptosis is one of the most prominent features of tumors and is highly related to SOX10 in tumor biology." (PMID 33344444, 2020). "These tumor cells were positive for a sox10:mCherry marker gene and injected into the pericardial cavity of transparent Casper recipient zebrafish embryos at 2 dpf." (PMID 32651197, 2020). "CD4+ and CD8+ T cells accumulated around the margin of the overt SOX10+ Melan A+ ITM but were largely excluded from the tumor centre." (PMID 31885869, 2019). "In line, expression of SOX10 transcription factor is the evidence of schwannian or melanocytic differentiation and again justifies the tumor’s recent designation." (PMID 30636233, 2018). "A panel of eight different markers was developed, including CD3, CD8, CD45RO, CD68, PD-1, PD-L1, FoxP3, as well as pan- cytokeratin and Sox10 as tumor markers." (PMID 30400835, 2018). "Previously, we demonstrated that SOX10 protein is required for tumor initiation, maintenance and survival." (PMID 29315345, 2018). "CAPE reduces chromatin accessibility at the mitfa promoter in sox10:Kaede+ cells, and Sox10 binds the mitfa promoter in a zebrafish tumor cell line." (PMID 28832322, 2017). "This tumor promoting effect seems to be related to the capacity of SOX10 to repress the anti-tumorigenic program mediated by the activity of the related factor SOX9." (PMID 29156643, 2017). "We chose to differentiate MHC-II+ from MHC-II− samples using a cutoff of >5% of tumour (SOX10+) membranes showing staining." (PMID 26822383, 2016). "Nine (75%) out of the 12 (22%) positive stage II-IV patients showed a positive SOX10 value closely correlated to tumor recurrence." (PMID 27110718, 2016). "It was also reported that SOX10 exhibits tumor suppressor activity by inducing tumor cell apoptosis, inhibiting invasion, and regulating cell epithelial to mesenchymal transition (EMT) in digestive cancers through suppressing Wnt/β-catenin signaling pathway." (PMID 27403158, 2016). "We therefore excluded patients with other malignancies, thus none of our patients would be expected to have SOX10 release from another SOX10 over expressing tumor." (PMID 27110718, 2016). "Dual-colour IHC was performed with HLA-DR and SOX10 to distinguish tumour versus stromal expression of HLA-DR." (PMID 26822383, 2016). "In this study, we report that SOX10 is a direct substrate of Fbxw7α E3 ubiquitin ligase, a tumor suppressor in multiple cancers." (PMID 26461473, 2015).
tumor (continued). "On the other hand, decreased expression of SOX10 was found to promote tumor cell growth and focal adhesions of Merlin-null schwannoma cells." (PMID 25301735, 2014). "The inhibitory effects of SOX10 on tumor growth were likely the result of apoptosis induction as revealed by TUNEL assay of HCT116 and KYSE150 xenografted tumor tissues." (PMID 25301735, 2014). "Compared to LV-GFP control group, expression of SOX10 significantly inhibited tumor growth in nude mice." (PMID 25301735, 2014). "SOX10 expression was further detected by IHC in multiple primary carcinomas and paired adjacent non-tumor tissue from the same patients." (PMID 25301735, 2014). "We found that SOX10 functions as a tumor suppressor by inducing tumor cell apoptosis, inhibiting invasion, regulating cell EMT and stemness through suppressing Wnt/β-catenin signaling." (PMID 25301735, 2014). "We found that ectopic expression of SOX10 suppressed tumor cell proliferation and tumorigenicity through promoting apoptosis in vitro and in nude mice." (PMID 25301735, 2014). "Cumulative outcomes from our above studies supported a key role of β-catenin inhibition in SOX10-induced tumor suppression of digestive tumor cells." (PMID 25301735, 2014). "In summary, our study identifies SOX10 as a functional tumor suppressor and an important regulator of the Wnt/β-catenin signaling pathway, with frequent epigenetic inactivation in certain digestive tumor." (PMID 25301735, 2014). "The IHC was performed on formalin-fixed and paraffin-embedded (FFPE) tissue slides from four GN and four NB tumours by using antibodies specific for Sox10 ([N-20], Santa Cruz Biotechnology) and ErbB-3 ([RTJ2], Abcam) respectively." (PMID 23835063, 2013). "Sox10 was positive in 94% of the cases (79 of 94 cases) in the tumor cells before chemotherapy and 91% (75 of 82 cases) after treatment." (PMID 24404438, 2013). "The tumor cells are positive for S-100 and SOX-10, with at least focal positivity for CD56." (PMID 40443852, 2025). "The rare SOX10+ labeling corresponded to TOM− SCs from tumor-infiltrating nerves." (PMID 41223283, 2025). "Similarly, curcumin‐induced upregulation of miR‐222 downregulates SOX10 levels, thereby inhibiting both tumor growth and metastatic potential through Notch signaling, which can activate MAPK and PI3K/AKT pathways while increasing N‐cadherin expression." (PMID 40458894, 2025). "The tumor tested negative for S100, SOX10, H3K27me3, and other markers associated with benign nerve sheath tumors." (PMID 40630199, 2025). "The results showed that high expression of SOX10 could promote oxidative phosphorylation and amino acid metabolism related pathways which accelerated energy metabolism in tumor cells." (PMID 40342816, 2025). "Additionally, SOX10 probably attenuated the tumor killing effect of T cells by blocking the T cell-mediated interferon-γ and JASK/STAT signaling pathways through inhibiting immune infiltration." (PMID 40342816, 2025). "Similarly, Sasaki proposed that overexpression of SOX10 significantly upregulated the expression of PD-L1 in tumor cells.Therefore, the relationship between SOX10 and immune checkpoints requires further exploration in future studies." (PMID 40342816, 2025). "However, the tumour cells displayed diffuse positivity for SOX10 and Prame, including in the rhabdoid areas." (PMID 40506928, 2025). "Another molecule that, according to some studies, might be even more specific and sensitive for diagnosing this tumor is SOX-10." (PMID 40722574, 2025). "Nevertheless, the tumour cells were diffusely positive for SOX10 and Prame." (PMID 40506928, 2025). "Although sox10 clearly reduced tumor initiation, we noted ‘escapers’." (PMID 40879132, 2025). "Given the complex regulation of gene expression, several key upregulated genes were found, including GATA4, SALL3, IL33, SOX10, and SCG3/SHC4, while the downregulation of keratin genes suggests a loss of epithelial differentiation, contributing to aggressive tumor behavior." (PMID 40647405, 2025).
tumor (continued). "Tumor cells were CK7+ S100+ SOX10+ p63 focally positive and p40‐." (PMID 41225782, 2025). "SOX10 was low expressed in a range of malignant tumor tissues except SKCM." (PMID 40342816, 2025). "Histology confirmed a low-grade tumour with unusual SOX10 expression." (PMID 41035732, 2025). "In contrast to the lack of binding around GE and interneuron genes, we observed strong signal for Foxr2 binding on promoters and regulatory elements of Sox9 and Sox10 in regions of open chromatin specific to glial-like tumor cells, correlating with expression of those genes in the RNA-seq data." (PMID 39495206, 2025). "Here, we showed that the suppression of SOX10 is sufficient to mediate the transition of OLC-like (SOX10-high/SOX9-low) to NSC-like (SOX10-low/SOX9-high) tumor phenotypes, in line with the roles of these transcription factors in determining cell-lineage identities during normal development." (PMID 39285246, 2024). "In dogs, Sox10 protein has been detected in peripheral nerves and associated tumors and has been proposed as a discriminative marker between canine PNST and perivascular wall tumor (PWT)." (PMID 38612342, 2024). "Tumour cells were positive for S-100 (100%, 41/41, 36 for diffuse positive and 5 for focal positive), diffuse SOX10 (100%, 23/23), p63 (100%, 43/43, 33 for diffuse positive and 10 for focal positive) and variable SMA (42%, 10/24) protein, whereas only a few patients were positive for p40 protein." (PMID 38982505, 2024). "We also observed heterogeneous intensity SOX10 staining in tumor cells." (PMID 38813332, 2024). "The tumor cells are typically surrounded by a network of thin blood vessels and supporting cells, also known as sustentacular cells, which are only recognizable if immunohistochemical stains are applied such as S100 or SOX10." (PMID 39569273, 2024). "One Sox10-positive tumor (4%) only showed additional positivity for SMA." (PMID 38612342, 2024). "The tumor cells show diffuse strong positivity for S100 and SOX10." (PMID 38803719, 2024). "As illustrated in the MM10 tumor, which bore the presence of a well-defined ZEB1high clone, increased ZEB1 expression was not only associated with low ZEB2 and MITF expression, but also with decreased SOX10 levels." (PMID 38519642, 2024). "Mammoglobin was expressed in 2 tumors (16%) and SOX10 was expressed in 1 tumor (8%)." (PMID 37306115, 2024). "TFE3 nuclear staining can also be observed in PEComa and granular cell tumour but MelanA, HMB45, PS100 and SOX10 are usually positive in these tumours, especially PEComa, which can sometimes share morphology closely resembling ASPS as well as alterations in the TFE3 locus." (PMID 38643139, 2024). "Intriguingly, SOX10 exhibits dual roles in these tumors, acting as a tumor suppressor and promoter." (PMID 38132479, 2023). "We used probes for NT5E and SOX10 on tumor sections and quantified expression across 5,600 cells." (PMID 37932277, 2023). "Urothelial carcinoma shows an overexpression of SOX10, indicating its role as a tumor promoter." (PMID 38132479, 2023). "In a similar fashion, SOX9 and SOX10 genes were expressed in the tumor mass, wherein Sox9-positive tumor cells were localized to the tumor rim and perivascular areas, while Sox10-positive tumor cells were limited to the tumor rim and rarely present in the inner area of the tumor." (PMID 38003507, 2023). "In addition, the proportion of PD-L1+ tumor cells (PD-L1+ PanCK/SOX10+) was unrelated to the PD-1+CD8+ subset cells." (PMID 36900182, 2023). "Since SOX10 has been shown to negatively correlate with PD-L1 expression on tumor cells, targeting SOX10 may not only enhance tumor cell ICD, but may also improve responses to anti-PD-1/-PD-L1 therapies by its direct effects on PD-L1 expression." (PMID 37626741, 2023). "The age, pathological grade, stage, and size of the tumor were correlated with SOX10 expression." (PMID 36120242, 2022).